HNRNPK (heterogeneous nuclear ribonucleoprotein K)
Diseases named in the same sentence as HNRNPK in open-access papers (continued):
Sharing a sentence is not in itself a finding about the gene and the disease.
colon carcinoma (13 papers, 2010 to 2024). "In patients with colon cancer, significant increases in both nuclear and cytoplasmic hnRNPK were observed among those with Dukes’ C stage." (PMID 33806648, 2021). "Moreover, p65BTK expression in colon cancer cells decreased upon silencing of hnRNPK by RNA interference." (PMID 26804170, 2016). "Finally, hnRNPK interacts with the MYU lncRNA, a c-Myc target that is overexpressed in colon cancer, to increase CDK6 transcription, as well as to promote the G1-S cell cycle transition during colon cancer, both of which are driven by Wnt/c-Myc signaling." (PMID 31110205, 2019). "Finally, we showed in paired peritumoural/tumoural samples from colon carcinoma patients that p65BTK expression parallels ERK1/2 activation and abnormal hnRNPK cytoplasmic localization." (PMID 26804170, 2016). "Taken together, our results suggest that p65BTK is an oncoprotein whose expression and transforming activity are tightly controlled, via hnRNPK, by the RAS/ERK pathway and that p65BTK overexpression in colon carcinomas reflects hyperactivation of the RAS/ERK pathway." (PMID 26804170, 2016). "D-finder identified a previously unknown D-site in heterogeneous nuclear ribonucleoprotein K (hnRNP-K), a transcriptional and translational regulator and known JNK/ERK substrate that is dysregulated in both colon cancer and leukemia." (PMID 20865152, 2010).
nasopharyngeal carcinoma (13 papers, 2009 to 2024). A carcinoma arising from the nasopharyngeal epithelium. "Overexpression of heterogeneous nuclear ribonucleoprotein K (hnRNP K), a DNA/RNA binding protein, is associated with metastasis in nasopharyngeal carcinoma (NPC)." (PMID 24885469, 2014). "Interestingly, hnRNPK has been previously reported to transcriptionally activate c-FLIP and antagonize TRAIL-induced apoptosis in nasopharyngeal carcinoma cells." (PMID 26972480, 2016).
pancreatic cancer (13 papers, 2011 to 2023). "Supporting our findings, recent studies have found that hnRNPK down‐regulation suppressed cell proliferation in pancreatic cancer 15 and renal cell carcinoma 18in vitro, but the underlying mechanism remains largely unknown." (PMID 27862976, 2017). "In bladder cancer, pancreatic cancer and renal cancer, studies have found that hnRNPK promotes cancer cell proliferation." (PMID 35875075, 2022). "In pancreatic cancer, the nuclear localization signal of HNRNPK transcriptionally drives the activation of YAP1 and regulates cancer progression." (PMID 36439880, 2022). "Supporting our findings, recent studies have found that HnRNPK downregulation suppresses cell proliferation in pancreatic cancer." (PMID 34857003, 2021). "For the first time, this provides a mechanistic explanation for the correlation between miR-223/FBXW7 and hnRNPK in pancreatic cancer." (PMID 28423622, 2017). "On the contrary, HNRNPK overexpression was found could increase pancreatic cancer cell proliferation, migration, and invasive." (PMID 31429522, 2019). "Serine and arginine-rich splicing factor 1 (SRSF1) and heterogeneous nuclear ribonucleoprotein K (hnRNPK) were aberrantly upregulated in pancreatic cancer, leading to the increased expression of anti-apoptotic splice variants of Bcl-x and Mcl-1, significantly affected responses to chemotherapy." (PMID 31552163, 2019).
Au-Kline syndrome (12 papers, 2018 to 2025). "Heterozygous pathogenic variants in HNRNPK cause Au-Kline syndrome (AUKS), a neurodevelopmental disorder characterized by congenital anomalies and developmental delay." (PMID 41216287, 2025). "Pathogenic HNRNPK variants cause Au-Kline syndrome (AKS), a neurodevelopmental disorder with malformations and distinctive facial features." (PMID 40304117, 2025). "In summary, this study identifies the first Chinese patient with a novel de novo heterozygous HNRNPK gene variant that contributes to Au-Kline syndrome and expands current knowledge of the clinical spectrum of HNRNPK variants." (PMID 35422839, 2022). "A young female patient (FIN6-3) was found to have a novel pathogenic frameshift variant [p.(Asp432fs)] in HNRNPK which is implicated in AD Au-Kline syndrome (AUKS) (OMIM # 616,580)." (PMID 33710394, 2021). "Mutations of hnRNPK were associated with AU-Kline syndrome associated with ID." (PMID 30283027, 2018). "The relationships between HNRNPK and diseases such as cancer, Kabuki-like syndrome, and Au-Kline syndrome have been described." (PMID 36261283, 2022). "Au-Kline syndrome (AUKS; OMIM 616580) is caused by heterozygous mutation in HNRNPK, the gene encoding the RBP hnRNP K, or a 264 kb deletion in chromosome 9q21.32 encompassing HNRNPK." (PMID 34564083, 2021). "Thus, we tested the phase separation ability of the three proteins, PQBP1 in Renpenning syndrome, HNRNPK in Au-Kline syndrome, and PAX6 in Aniridia." (PMID 38225666, 2024).
leukemia (12 papers, 2010 to 2025). A malignant (clonal) hematologic disorder, involving hematopoietic stem cells and characterized by the presence of primitive or atypical myeloid or lymphoid cells in the bone marrow and the blood. "Overall, a high proportion of co-regulated genes in the three regulatory models of HNRNPK are associated with neoplastic process, some of which are associated with leukemia, indicating that HNRNPK is a key factor in CML." (PMID 36052164, 2022). "This study is, to the best our knowledge, the first study that demonstrates RCMTs/hnRNPK-mediated lineage-associated drug-responsive chromatin structure in leukaemia cells." (PMID 29563491, 2018). "The expression levels of hnRNPK, NSUN1 and BRD4 were also linked to leukaemia progression and implicated in both 5‐AZA resistance and cancer advancement." (PMID 40008496, 2025). "Together, these data suggest selective interactions between hnRNPK and various RCMTs to form distinct functional complexes important for integrity of these proteins and survival of the leukaemia cells." (PMID 29563491, 2018). "Binding of the endogenous hnRNPK to unmethylated and cytosine-methylated RNA was also demonstrated using nuclear lysate from human leukaemia cells." (PMID 29563491, 2018). "Knockdown of hnRNPK or any of the RCMTs significantly inhibited the growth of SC leukaemia cells." (PMID 29563491, 2018). "Although a vast majority (~90%) of 5-AZA is incorporated into RNA32, it is still unknown whether RNA:m5C, RCMTs and hnRNPK play a role in the response/resistance to 5-AZA in leukaemia cells." (PMID 29563491, 2018). "In a recent report, NSUN3 was found to form a complex with hnRNPK, DNMT2 and P‐TEFb at elongating RNA polymerase II sites in leukemia cells implying a role for NSUN3 in transcriptional regulation in the nucleus." (PMID 30311405, 2019). "In contrast, siRNA knockdown of NSUN1 or NSUN2 significantly reduced both the NSUN1 and NSUN2 proteins, but had little effects on the hnRNPK/NSUN3/DNTM2 complex and total RNA-pol-II in the leukaemia cells." (PMID 29563491, 2018). "Knockdown experiments with the siRNAs targeting various RCMTs demonstrated that downregulation of hnRNPK, NSUN3 and DNMT2 preferentially inhibited the growth of the 5-AZA-sensitive SC leukaemia cells (top)." (PMID 29563491, 2018). "RNase digestion-coupled IP and co-IP revealed a direct interaction between hnRNPK and CDK9/P-TEFb and indirect interactions between hnRNPK and CDK7/TFIIH as well as RNA-pol-II CTD-S2P in the OCI-M2 leukaemia cells." (PMID 29563491, 2018). "In contrast, the interactions between hnRNPK and DNMT2 as well as NSUN3 were insensitive to 5-AZA in the same leukaemia cells." (PMID 29563491, 2018). "Our data together suggest that RNA and hnRNPK mediate 5-AZA-sensitive interactions between the lineage-determining factors (GATA1 and SPI1/PU.1) and chromatin modifiers in the OCI-M2 and SC leukaemia cells." (PMID 29563491, 2018). "RNase digestion-coupled immunoprecipitation (IP) and co-immunoprecipitation (co-IP) demonstrated RNA-independent, direct binding of hnRNPK to a subset of RCTMs, namely, DNMT2 and NSUN3, in OCI-M2 leukaemia cells." (PMID 29563491, 2018). "Additionally, studies in leukemia have shown that NSUN3 and DNMT2 can regulate the chromatin structures by directly binding hnRNPK and further modulating 5-Azacitidine response." (PMID 37666951, 2023). "Our data demonstrate that hnRNPK directly interacts with a subset of RCMTs, namely DNMT2 and NSUN3, to form a functional complex important for the integrity of these proteins and survival of leukaemia cells." (PMID 29563491, 2018). "In contrast, no appreciable interactions between hnRNPK and NSUN1 or NSUN2 were detected in OCI-M2 leukaemia cells." (PMID 29563491, 2018).
viral infection (12 papers, 2013 to 2025). "The heterogeneous nuclear ribonucleoprotein K (hnRNP K) that shuttles between the nucleus and cytoplasm plays an important role in viral infection." (PMID 35875542, 2022). "Regarding proteomics in patients with PHN, some upregulated proteins (HNRNPK and RPS10) were related to viral infection and replication." (PMID 36277496, 2022).
neuroblastoma (10 papers, 2015 to 2023). Neuroblastoma (NB) is the most common solid, extracranial childhood tumor. "For example, Ets-1 promoter-associated noncoding RNA (pancEts-1) is overexpressed in NB, and promotes neuroblastoma progression through hnRNPK-mediated β-catenin stabilization." (PMID 31787850, 2019). "lncRNA pancEts-1 contributed to neuroblastoma development through hnRNPK-induced β-catenin stabilization." (PMID 38111678, 2023). "To study this, we knocked down hnRNPK using an siRNA in SH-SY5Y neuroblastoma cells, and performed RNA sequencing (three replicates of each condition)." (PMID 34274995, 2021). "For instance, long non-coding RNA facilitates hnRNPK-mediated stability and transactivation of β-catenin in neuroblastoma cells." (PMID 33806648, 2021). "In neuroblastoma cells, the direct binding of panc-Ets-1 to hnRNPK favors the interaction with β-catenin, thus resulting in β-catenin stabilization and transactivation, to assist tumor invasion and metastasis." (PMID 32722129, 2020). "For example, long noncoding RNA pancEts-1 accelerates neuroblastoma progression via hnRNPK-mediated stabilization of β-catenin." (PMID 31431517, 2019). "Indeed, inhibition of hnRNPK by antibodies increases cell spreading and silencing of hnRNPK in differentiated N2A neuroblastoma cells increases the number and length of their neurites." (PMID 26305187, 2015). "In addition, hnRNPK directly interacts with β-catenin, resulting in the stabilization and transactivation of β-catenin, which promotes the growth, invasion, and metastasis of neuroblastoma cells." (PMID 33806648, 2021).
acute myeloid leukemia (9 papers, 2019 to 2025). Acute myeloid leukemia (AML) is a group of neoplasms arising from precursor cells committed to the myeloid cell-line differentiation. "For instance, point mutations and deletions in the HNRNPK gene, causing hnRNP K down-regulation, have been suggested to have a role in the development of acute myeloid leukemia." (PMID 32596243, 2020). "On the contrary, hnRNPK serves as a tumor suppressor gene in acute myeloid leukemia (AML), as evidenced by the susceptibility of hnRNPK heterozygous mice to AML and lymphoma." (PMID 35352475, 2022). "HNRNPK mutation in humans causes a Kabuki-like syndrome with skeletal abnormalities and facial dysmorphism; patients with acute myeloid leukemia show aberrant hnRNPK expression." (PMID 36735291, 2023). "Clinical and preclinical studies suggest that both the overexpression and underexpression of hnRNPK similarly contribute to the progression of acute myeloid leukemia (AML)." (PMID 40775642, 2025).
bladder cancer (8 papers, 2017 to 2024). "To further evaluate the prognostic factors associated with overall survival in bladder cancer, we first carried out univariate analysis using age, sex, tumour stage, histological grade, node stage, tumour size and hnRNPK expression as parameters." (PMID 27862976, 2017). "Loss‐ and gain‐of‐function assays demonstrated that hnRNPK promoted proliferation, anti‐apoptosis, and chemoresistance in bladder cancer cells in vitro, and hnRNPK knockdown suppressed tumorigenicity in vivo." (PMID 27862976, 2017). "Our findings strongly suggest that hnRNPK participates in bladder cancer carcinogenesis and is a potential diagnostic and prognostic marker and a promising therapeutic target." (PMID 27862976, 2017). "Furthermore, HNRNPK is involved in the tumorigenesis of multiple cancer types, with specific lncRNA association of hnRNP-K previously shown to either promote or inhibit self-renewal in bladder-cancer stem-like cells." (PMID 37554968, 2023). "Furthermore, high nuclear hnRNPK expression was associated with poor prognosis and served as an independent predictor of overall survival in bladder cancer." (PMID 27862976, 2017). "However, the expression and biological functions of hnRNPK underlying tumorigenesis and progression in bladder cancer remain unknown." (PMID 27862976, 2017). "HNRNPK expression has also been shown to be upregulated in bladder cancer and correlate with poor clinical outcome in patients." (PMID 37554968, 2023). "To investigate the mechanism of hnRNPK in bladder cancer, we performed RNA‐seq to analyse the changes in target gene mRNA levels between UM‐UC‐3 cells that had been transfected with si‐hnRNPK or control siRNA." (PMID 27862976, 2017). "To further explore the effects of hnRNPK in bladder cancer tumorigenesis in vivo, we stably suppressed hnRNPK in UM‐UC‐3 cells by lentiviral transfection." (PMID 27862976, 2017). "In this study, we investigated hnRNPK expression in bladder cancer tissues and analysed its correlation with the clinicopathological characteristics and overall survival of bladder cancer." (PMID 27862976, 2017). "Heterogeneous nuclear ribonucleoprotein K is mainly expressed in the nuclei of bladder cancer cells." (PMID 27862976, 2017). "As hnRNPK is mainly expressed in the nuclei of bladder cancer cells, we focused on its function in the nucleus and used RNA‐seq to explore the target genes." (PMID 27862976, 2017). "In conclusion, we discovered that hnRNPK plays an important role in bladder cancer, suggesting that it is a potential prognostic marker and a promising target for treating bladder cancer." (PMID 27862976, 2017). "Collectively, these results indicate that hnRNPK knockdown inhibits bladder cancer cell proliferation by inducing G0/G1 arrest." (PMID 27862976, 2017). "In conclusion, it is our novel discovery that hnRNPK is up‐regulated in bladder cancer and correlates with poor prognosis." (PMID 27862976, 2017). "Here, we discovered that hnRNPK knockdown significantly inhibited bladder cancer cell proliferation in vitro and tumour growth in vivo by inducing G0/G1 arrest." (PMID 27862976, 2017). "To detect hnRNPK expression in bladder cancer, we first performed western blot analysis on six cases of primary bladder cancer." (PMID 27862976, 2017). "To further evaluate hnRNPK expression and its relationship with the clinical features of bladder cancer, we examined hnRNPK expression in 188 bladder cancer tissues and 102 normal tissues by IHC." (PMID 27862976, 2017). "In this study, we found that hnRNPK knockdown increased apoptosis and sensitized bladder cancer cells to cisplatin." (PMID 27862976, 2017). "We show for the first time that increased expression of nuclear hnRNPK in bladder cancer cells is positively correlated with poor differentiation and advanced tumour stage." (PMID 27862976, 2017).
bladder cancer (continued). "Mechanistically, hnRNPK regulated various functions in bladder cancer by directly mediating cyclin D1, G0/G1 switch 2 (G0S2), XIAP‐associated factor 1, and ERCC excision repair 4, endonuclease catalytic subunit (ERCC4) transcription." (PMID 27862976, 2017). "Heterogeneous nuclear ribonucleoprotein K was mainly expressed in the nuclei of the bladder cancer cells and was significantly overexpressed in bladder cancer tissues as compared with normal tissues (score: 143.3 ± 5.7 versus 95.3 ± 5.8, P < 0.001)." (PMID 27862976, 2017). "Taken together, these data indicate that hnRNPK regulates target genes in bladder cancer by directly mediating transcription." (PMID 27862976, 2017). "In this study, we found that hnRNPK is mainly expressed in the nucleus and rarely detected in the cytoplasm of bladder cancer cells." (PMID 27862976, 2017). "To study the role of hnRNPK in bladder cancer, we suppressed hnRNPK in bladder cancer cells via siRNA transfection." (PMID 27862976, 2017). "Collectively, these findings indicate that hnRNPK enhances bladder cancer cell anti‐apoptosis and chemoresistance to cisplatin by regulating XAF1 and ERCC4 and that it may be a potential target for drug development." (PMID 27862976, 2017). "Taken together, high‐hnRNPK expression levels may serve as a novel prognostic marker for bladder cancer." (PMID 27862976, 2017). "Interestingly, the genes regulated by hnRNPK were mainly enriched in signal transduction, cell cycle, response to DNA damage and apoptosis, which is consistent with cellular function in bladder cancer." (PMID 27862976, 2017). "We also studied the function and mechanism of hnRNPK in bladder cancer cells." (PMID 27862976, 2017). "However, both the expression patterns and biological mechanisms of hnRNPK in bladder cancer are unclear." (PMID 27862976, 2017). "Kaplan–Meier survival analysis showed significantly reduced overall survival (P = 0.0133, median survival, 26 months) in patients with bladder cancer with increased hnRNPK expression as compared with the median overall survival of 57 months in patients with low hnRNPK immunostaining." (PMID 27862976, 2017). "Therefore, hnRNPK is a potential biomarker for bladder cancer and a promising target for drug development." (PMID 27862976, 2017). "Moreover, hnRNPK promotes bladder cancer cell proliferation, anti‐apoptosis and chemoresistance to cisplatin by regulating a series of genes at transcriptional level." (PMID 27862976, 2017). "We investigated hnRNPK expression by immunohistochemistry in 188 patients with bladder cancer, and found that hnRNPK expression levels were significantly increased in bladder cancer tissues and that high‐hnRNPK expression was closely correlated with poor prognosis." (PMID 27862976, 2017). "However, the function of hnRNPK in mRNA splicing and the cytoplasm remains largely unknown, and further investigation is underway to elucidate these key questions in bladder cancer." (PMID 27862976, 2017). "However, different expression levels of HNRNPK do not affect the overall survival of patients with bladder cancer." (PMID 35130920, 2022). "However, hnRNPK knockdown did not affect XIAP mRNA levels in bladder cancer cells (data not shown), suggesting that the mechanism of hnRNPK on apoptosis differs between cancers." (PMID 27862976, 2017). "Until now, there has been no report on hnRNPK behaviour in bladder cancer." (PMID 27862976, 2017).